ICOS (inducible T cell costimulator)
Diseases named in the same sentence as ICOS in open-access papers (continued):
Sharing a sentence is not in itself a finding about the gene and the disease.
liver fibrosis (2 papers, 2015 to 2024). "In this study, we utilized ICOSL-KO mice and primary HSCs to demonstrate that the ICOSL/ICOS signaling pathway plays a critical role in the activation of HSCs and liver fibrosis following S. japonicum infection by regulating specific lncRNAs." (PMID 39044218, 2024). "Our previous study showed that downregulation of ICOS signaling alleviated liver fibrosis lesions in mice infected with S. japonicum." (PMID 39044218, 2024). "Previous experiments have shown that the expression of relevant lncRNAs can be influenced by ICOSL/ICOS intervention during the course of liver fibrosis in S. japonicum-infected mice." (PMID 39044218, 2024). "All results indicate that ICOSL/ICOS pathway-regulated lncRNAs on liver fibrosis in mice infected with Schistosoma japonicum." (PMID 39044218, 2024). "The present study used the ICOSL KO mice to assess the role of the ICOSL/ICOS interaction in the mediation of the Th17 response in host granulomatous inflammation, particularly in liver fibrosis during S.japonicum infection." (PMID 25590646, 2015). "Our previous research indicated that downregulating the ICOSL/ICOS could partially alleviate liver fibrosis." (PMID 39044218, 2024). "This study uncovers that ICOSL/ICOS may play a role in activating hepatic stellate cells and promoting liver fibrosis in mice infected with Schistosoma japonicum by dynamically regulating the expression of specific lncRNAs." (PMID 39044218, 2024). "This suggests that ICOSL/ICOS signaling may promote HSCs activation and liver fibrosis by reducing the expression of antifibrotic lncRNAs." (PMID 39044218, 2024). "Hence, we aim to establish an S. japonicum infection model using ICOSL knock out (ICOSL-KO) and C57BL/6 wild-type mice to explore whether the ICOSL/ICOS signaling pathway modulates specific lncRNAs to participate in HSCs activation, thereby influencing the progression of liver fibrosis." (PMID 39044218, 2024). "This study reveals the dynamic role of lncRNA-H19, -MALAT1, -PVT1, -P21, and -GAS5 in HSCs activation and liver fibrosis in S. japonicum-infected mice, regulated by the ICOSL/ICOS signaling pathway." (PMID 39044218, 2024).
metastatic tumor (2 papers, 2018 to 2023). "Furthermore, the density of PD-1+, ICOS+ and Granzyme B+ TILs, a marker of immune escape/activation, in the primary tumor was associated with that in the metastatic tumor." (PMID 29614981, 2018). "Although it did not apply to all of the markers, some of the activation/suppression marker values (i.e., ICOS and Granzyme B) of the primary tumor were significantly correlated with those of the metastatic tumor." (PMID 29614981, 2018). "Decreased memory B cells, CD8+T cells and Tregs, and increased M0 and M2 macrophages in a fraction of metastatic tumors with a high PD-L2/ICOS ratio, may suggest future prospective therapeutic trials in this patient subpopulation." (PMID 36983005, 2023). "The median values of CTLA4+, ICOS+, and GITR+ TILs in the primary tumor were significantly higher than those in the metastatic tumor." (PMID 29614981, 2018). "Furthermore, the activation/suppression marker values of the lymphocytes (i.e., such as PD-1, ICOS, Granzyme B and the PD-1/CD8 ratio) in the primary tumor were correlated with values in the metastatic tumor." (PMID 29614981, 2018).
Neuromyelitis Optica Spectrum Disorder (2 papers, 2020 to 2025). "In the early stages of neuromyelitis optica spectrum disorders (NMOSDs), membrane-bound ICOS/ICOSL, membrane-bound PD-1/PD-L1, soluble sICOSL, and soluble PD-1/PD-L1 also exhibited significant upregulation." (PMID 40352922, 2025).
Opportunistic infection (2 papers, 2017 to 2019). An infection that is caused by a pathogen that would generally not be able to cause an infection in a host with a normal immune system. "Our findings are also in agreement with the decreased NK cell counts and the increased susceptibility to viral and opportunistic infection, as well as cancer recently described in ICOS- or ICOS-L-deficient humans." (PMID 31283790, 2019). "The clinical phenotype of ICOS deficiency is much broader than initially anticipated and includes not only CVID-like disease but an increased susceptibility to viral and opportunistic infections, as well as cancer." (PMID 28861081, 2017). "None of the other ICOS-deficient patients had frankly opportunistic infections or showed signs of a severe T-cell deficiency." (PMID 28861081, 2017).
osteoarthritis (2 papers, 2018 to 2022). A noninflammatory degenerative joint disease occurring chiefly in older persons, characterized by degeneration of the articular cartilage, hypertrophy of bone at the margins and changes in the synovial membrane. "In particular, we show that CD3/ICOS costimulation plays a major role in pathways related to STAT3 function and osteoarthritis (OA), whereas the CD3/CD28 axis mainly regulates p38 MAPK signaling." (PMID 36131938, 2022).
ovarian tumors (2 papers, 2020 to 2023). "The increased expression of SIGLEC1 is closely related to tumor formation and metastasis, and the increased expression of ICOS leads to poor prognosis and significantly increased PDCD1 expression in ovarian tumors." (PMID 37895197, 2023).
peripheral T-Cell lymphoma (2 papers, 2023). "Importantly, the established SS PDX model exhibited a stable immunophenotype and expressed several cell surface targets (ICOS, PD-1, TRBC1 and KIR3DL2) that are currently the subject of early clinical investigation in peripheral T-cell lymphoma." (PMID 37718909, 2023).
psoriatic arthritis (2 papers, 2022 to 2023). Joint inflammation associated with psoriasis. "The simultaneous inhibition of ICOS and CD28 signaling, achieved through the use of inhibitors like Acazicolcept, has proven effective in reducing inflammation and slowing the progression of RA and psoriatic arthritis (PsA)." (PMID 38041172, 2023).
pulmonary arterial hypertension (2 papers, 2022). Pulmonary arterial hypertension (PAH) is a group of diseases characterized by mean pulmonary artery pressure >20 mmHg and elevated pulmonary arterial resistance leading to right heart failure. "Indeed, the main finding of our study is the observation that the soluble ICOS and ICOSL are both increased in patients with pulmonary arterial hypertension; it is particularly interesting that this finding is not dependent on the underlying cause of PAH." (PMID 35328257, 2022).
pulmonary sarcoidosis (2 papers, 2020 to 2022). Sarcoidosis affecting the lung parenchyma. "Finally, a high expression level of ICOS was demonstrated in lung Tregs of pulmonary sarcoidosis patients." (PMID 35328257, 2022).
renal cell carcinoma (2 papers, 2019 to 2023). "Additionally, the TMB, MSI, MMR, and DNMT genes as well as ICOS expression are linked in many cancer types.The results of PCR showed that it is highly expressed in gastric, breast, liver and renal cell carcinoma cell lines compared with normal cells." (PMID 36855091, 2023).
Splenomegaly (2 papers, 2014 to 2023). Abnormal increased size of the spleen. "Interestingly, the partial reduction of ICOS expression was accompanied by a reduction of lymphadenopathy, splenomegaly, total T- and B-cell number, and germinal center B cell number thus demonstrating that overexpression of ICOS contributes to sanroque mice autoimmune phenotype." (PMID 24917867, 2014).
triple-negative breast carcinoma (2 papers, 2021 to 2023). An invasive breast carcinoma which is negative for expression of estrogen receptor (ER), progesterone receptor (PR), and human epidermal growth factor receptor 2 (HER2). "ICOS demonstrates significant overexpression in triple-negative breast cancer (TNBC) patients, as well as in the basal-like and HER2+ subtypes in the TCGA cohort, which is also well validated in the METABRIC cohort." (PMID 38127899, 2023).
uterine corpus endometrial carcinoma (2 papers, 2021 to 2023). A endometrial carcinoma (disease) that involves the body of uterus. "Regarding uterine corpus endometrial carcinoma (UCEC), we observed a young-bias pattern concerning immune checkpoints (CTLA-4, ICOS, and so on) and CYT (p=0.013) and validated it in an independent dataset." (PMID 33936087, 2021).
Achalasia (1 paper, 2023). A disorder of esophageal motility characterized by the inability of the lower esophageal sphincter to relax during swallowing and by inadequate or lacking peristalsis in the lower half of the body of the esophagus. "Besides, many co-inhibitory molecules, including PDCD1, HAVCR2, LAG3, ICOS, PRDM1, and MAF, were markedly downregulated in TRM, supporting an activated cell state in achalasia." (PMID 37542039, 2023).
Adult onset (1 paper, 2015). Onset of disease manifestations in adulthood, defined here as at the age of 16 years or later. "A homozygous 1815 base-pair deletion in the ICOS-encoding gene ICOS was reported in 2003 as the cause of adult-onset autosomal recessive common variable immunodeficiency in multiple patients from the Danube region." (PMID 26399252, 2015).
airway hyperresponsiveness (1 paper, 2013). "IL-35, a novel heterodimeric cytokine comprised of the IL-12α (p35) and EBV-induced gene product (EBI-3) subunits, has also been associated with high ICOS expressing Treg in a mouse model of airway hyperresponsiveness." (PMID 23967339, 2013).
alopecia areata (1 paper, 2021). Loss of scalp and body hair involving microscopically inflammatory patchy areas. "Our data show that rs4404254 and rs4675379 SNPs of ICOS gene are associated with Alopecia Areata and also reveal that the presence of rs4404254 polymorphism correlates with ICOS post‐transcriptional repression by microRNA binding." (PMID 35664973, 2021).
amoebiasis (1 paper, 2021). "Multiple pathways were potentially regulated by several hub genes; for example, ICOS, HLA − A, and CD40LG were related to regulate allograft rejection and cell adhesion molecules; IL10 was related to regulate allograft rejection, amoebiasis, and hematopoietic cell lineage." (PMID 34603484, 2021).
aneurysm (1 paper, 2024). Bulging or ballooning in an area of an artery secondary to arterial wall weakening. "Furthermore, it has been observed that MDSCs, through the ICOSL/ICOS axis, can promote aneurysms by promoting Th17 cells." (PMID 39769367, 2024).
angiosarcoma (1 paper, 2024). A malignant tumor arising from the endothelial cells of the blood vessels.
aortic aneurysm (1 paper, 2022). A ruptured aneurysm located in the wall of the proximal portion of the descending aorta proceeding from the arch of the aorta. "FOXP3+ Treg cells were abundant in aortic aneurysms, especially in AAA groups and displayed high expression of exhausted genes CTLA4, TIGIT, TNFRSF14, ICOS, and CD28." (PMID 36703732, 2022).
arteriosclerosis (1 paper, 2007). A vascular disorder characterized by thickening and hardening of the walls of the arteries. "Additionally, blockade of ICOS using an anti-ICOS antibody in conjunction with cyclosporine administration led to sustained allograft survival without the development of transplant arteriosclerosis." (PMID 17711408, 2007).
atopic asthma (1 paper, 2011). An asthma that is characterized by symptoms that are triggered by an allergic reaction caused by inhaled allergens such as dust mite allergen, pet dander, pollen and mold. "Understanding how ICOS regulates the development and the survival of EM CD4 cells may enhance novel vaccination strategies aimed at inducing protective EM CD4 T cells and regulatory strategies to control CD4 responses in diseases such as atopic asthma that are exacerbated by EM CD4 T cells." (PMID 21364749, 2011).
autoimmune neuropathy (1 paper, 2024). An autoimmune form of peripheral neuropathy. "In an adoptive transfer model of autoimmune neuropathy, we found that 79-6 treatment was accompanied by a decrease in the frequency of nerve-infiltrating Tph (CD4+ICOS+CXCR5–PD-1+CXCR6+) cells compared with vehicle treatment." (PMID 39087473, 2024).
autoinflammatory syndrome (1 paper, 2013). A group of disorders of the innate immune system characterized by attacks of seemingly unprovoked inflammation without significant levels of either autoantibodies or autoreactive T cells more characteristic of autoimmune disease. "Also, the expression of key surface molecules by TR2-deficient Treg cells—namely CTLA-4, GITR (Tnfrsf18), and ICOS —remained unchanged in contrast to our observations in the bone marrow chimera model presenting with a lethal autoinflammatory syndrome." (PMID 24115907, 2013).
B-cell chronic lymphocytic leukemia (1 paper, 2019). "In addition, a previous study indicated that compared with ICOS rs10932029 TT genotype, ICOS rs10932029 CT genotype was associated with a higher rate of disease progression in B-cell chronic lymphocytic leukemia patients." (PMID 31235485, 2019).
bladder tumors (1 paper, 2019). "PD-1 and ICOS are also co-expressed on T cells in human bladder tumors." (PMID 31412943, 2019).
Brain tumor (1 paper, 2020). "Brain tumor volumes ranged from 0 to 300 mm3 and were found to be inversely correlated to the density of intratumoral PD-1+ TILs (P < .05), and, although not statistically significant, a trend toward correlation for ICOS+ TILs was observed (P = 0.058)." (PMID 32642679, 2020).
cervical disease (1 paper, 2021). "What stood out in the tables was the patients afflicted with the cervical disease showed positive correlation significantly, such as famous immune checkpoint genes (CTLA4, TIGIT, HAVCR2, LAG3, etc.)and costimulatory genes like ICOS, CD80, CD40, and so forth." (PMID 33694292, 2021).
cervical squamous cell carcinoma (1 paper, 2024). A squamous cell carcinoma arising from the cervical epithelium. "In cervical squamous cell carcinoma (CESC), ICOS, KIR2DL4, TNFSF9, and CD86 function in immune activation and display a negative association with METTL3 expression." (PMID 39199429, 2024).
Chlamydia infection (1 paper, 2012). "Therefore, further study of the PI3K-dependent and -independent ICOS signaling pathways related to IL-17/Th17 responses in Chlamydia infection is important to better understand the mechanism of ICOS-ICOSL signaling in modulating host defense." (PMID 23285133, 2012). "Congruent to our previous results obtained with ICOSL-KO mice, we confirmed that ICOS-KO mice experienced more severe weight loss, delayed bacterial clearance, and lung pathology with heightened Th1/IFN-γ responses during Chlamydia infection compared to WT mice." (PMID 23285133, 2012). "To gain more insight into the molecular basis of ICOS function during the clearance of Chlamydia infection, we analysed immune responses during pulmonary infection of Chlamydia muridarum in ICOS-WT, ICOS-KO, and ICOS-YF mice in a Chlamydia-resistant C57BL/6 background." (PMID 23285133, 2012).
chlamydial infection (1 paper, 2012). "We confirmed that ICOS-KO mice have the same phenotypes as ICOSL-KO mice following chlamydial infection, consistent with the notion that ICOSL is the sole ligand of ICOS." (PMID 23285133, 2012).
chronic allograft nephropathy (1 paper, 2021). "We previously reported glomerular infiltration by CXCR3+ ICOS+ activated T cells in chronic allograft nephropathy with TG." (PMID 34207555, 2021).
chronic hepatitis (1 paper, 2024). An active inflammatory process affecting the liver for more than six months. "Interestingly, our results also revealed a tendency of increased expression of intrahepatic PD-1+ and ICOS+ NK cells and mainly the significant increase of 4-1BB+ NK cells in the chronic hepatitis group compared to control." (PMID 39882238, 2024). "Our study revealed that ICOS is mainly expressed in intrahepatic NK cells of HBeAg+ chronic hepatitis patients and that the expression is linked to the CD56brightCD16− NK cells, while the CD56dimCD16+ NK cell subset seems to be ICOS negative." (PMID 39882238, 2024). "In contrast, TIM-3, ICOS, and 4-1BB-positive CD8+ T cells as well as PD-1, TIM-3, and 4-1BB-positive CD4+ T cells were enriched mainly in the liver of chronic hepatitis patients." (PMID 39882238, 2024).
Cirrhosis (1 paper, 2015). A chronic disorder of the liver in which liver tissue becomes scarred and is partially replaced by regenerative nodules and fibrotic tissue resulting in loss of liver function. "In the present study, circulating ICOS+ Tfh cells were associated with cirrhosis status." (PMID 26517519, 2015). "The frequencies of ICOS+ and CCR7+ CXCR5+CD45RA−CD4+ T cells were higher in HCC patients than in HC (P = 0.002 and P < 0.001, respectively), and the percentage of ICOS+ Tfh cells was correlated with the incidence of cirrhosis in HCC patients (P = 0.039)." (PMID 26517519, 2015). "However, paired comparison showed that the percentage of ICOS+ Tfh cells was higher in tumor tissues than in para-tumor tissues, implying that the tumor environment rather than cirrhosis status caused the increase in ICOS+ Tfh cells." (PMID 26517519, 2015).
coinfection (1 paper, 2024). The simultaneous infection of a host by multiple pathogen species. "Distinctly, VL1 patient, that has disorganized spleen and VL-HIV coinfection was related to SOD1, STAT3, STAT4, ICOS, TRAF6 and IRF3 genes, and CD8+ cells in the RP and expression of IL6 in both regions of spleen." (PMID 38843306, 2024).
dementia (1 paper, 2022). Loss of intellectual abilities interfering with an individual's social and occupational functions. "Therefore, we wanted to determine whether also the expression of the T cell co-stimulatory markers CD28, ICOS and CTLA-4 was affected by dementia." (PMID 34427746, 2022).
diffuse large B-cell lymphoma (1 paper, 2023). "MiR-21 expression was significantly elevated in the serum of diffuse large B-cell lymphoma (DLBCL) patients, and it promoted inducible co-stimulator (ICOS) expression on Tregs, thereby assisting the COS ligand (ICOSL) on endothelial cells to crosstalk with Tregs." (PMID 37671150, 2023).
DiGeorge Syndrome (1 paper, 2018). "There are no significant changes in ICOS expression on any measured T cell population of DiGeorge syndrome patients." (PMID 30083170, 2018).
emphysema (1 paper, 2025). "From these results, it was assumed that ICOS-mediated CD4+ T cell activation exacerbated lung dysfunctions such as geriatric emphysema that was a risk predisposition for ICI-induced pneumonitis." (PMID 40198121, 2025).
esophageal squamous cell carcinoma (1 paper, 2024). Esophageal squamous cell carcinoma (ESCC) is a type of esophageal carcinoma (EC) that can affect any part of the esophagus, but is usually located in the upper or middle third. "Moreover, when circulating Tfh cells and regulatory T (Tfr) cells are cocultured with PD-L1-EVs from esophageal squamous cell carcinoma, ICOS expression increases only on Tfr cells, consistent with the distinct functions of ICOS on these cells." (PMID 39528800, 2024).
gout (1 paper, 2023). A condition characterized by painful swelling of the joints, which is caused by deposition of urate crystals. "In contrast, we discovered that the THBS, NOTCH, and ICOS signaling pathways were downregulated during gout flares." (PMID 38063198, 2023). "In this study, we also observed that Tregs produced during gout remission highly expressed CTLA4 and ICOS, which further prompted us to examine the interaction between Tregs and APCs." (PMID 38063198, 2023). "Interestingly, we found that inhibitory genes, such as CTLA4 and inducible costimulator (ICOS), were significantly upregulated during gout remission." (PMID 38063198, 2023). "As such, we postulated that an increase in Tregs during gout remission may enhance the suppressive function of Tregs, which is potentially mediated by CTLA4 and ICOS." (PMID 38063198, 2023).